CD4 (CD4 molecule)
Diseases named in the same sentence as CD4 in open-access papers (continued):
Sharing a sentence is not in itself a finding about the gene and the disease.
cardiovascular disease (continued). "One might also expect age-adjusted cardiovascular disease mortality to have decreased during the study period along with changes in cardiovascular disease risk factor management, thus obfuscating a potential association with a CD4 count." (PMID 34886257, 2021). "Furthermore, a low CD4/CD8 ratio has been proposed to be a marker for age-associated complications including cardiovascular diseases." (PMID 30755782, 2019). "CD4 T-cell abnormality was associated with the cardiovascular disease in ESRD patients." (PMID 28726529, 2017). "A low CD4+ cell count was found to be a risk factor for cardiovascular disease events." (PMID 25727038, 2015). "However, even relatively small reductions from normal CD4 counts in HIV-infected patients have been associated with increased risk of cardiovascular disease and malignancies." (PMID 24204216, 2013). "Also, the use of statins in patients with cardiovascular disease was associated with both a lowered C-reactive protein and a reduced frequency of circulating of CD4+CD28null T cells." (PMID 24288592, 2013). "Participants were matched on age, sex, BMI, current smoking status, time since HIV diagnosis, time on cART, CD4 nadir, most recent CD4 count, current use of cholesterol lowering medication and medical history of cardiovascular disease." (PMID 38675924, 2024). "Treg, with the secretion of anti-inflammatory IL-4, IL-10, and TGF-β, has been generally recognized as the crucial CD4+ T cell for the balance of systemic inflammation and relevant cardiovascular diseases." (PMID 36678161, 2023). "The predominant expression of Dpp4 in T cells and upregulation of Dpp4 in aorta‐infiltrating CD4+ T lymphocytes from patients with cardiovascular disease were also noted in the single cell RNA sequencing data obtained from PlaqView." (PMID 36683148, 2023). "Apart from traditional risk factors, traits associated with HIV infection, including low CD4 + T-cell count, inflammatory response associated with HIV infection and some antiretroviral therapies, are independently related to cardiovascular disease." (PMID 36088434, 2022). "CD4+CD28-NKG2D+ T cells producing IL-17 have been documented in inflammation-associated diseases, including T2DM and cardiovascular diseases." (PMID 35159268, 2022). "Age > 50 years, intravenous drug use (IDU), family history of cardiovascular disease, HIV-RNA > 50, CD4 < 200, were associated with a higher hospitalization risk." (PMID 34362172, 2021). "Even more, it has been postulated that an expansion of cytotoxic CD4 T cells drives cardiovascular disease in certain inflammatory conditions and they are triggered by CMV infection." (PMID 33777054, 2021). "Over-activation of CD4+ T cells and disproportion of their subpopulations play an important role in the pathogenesis of various cardiovascular diseases." (PMID 30770790, 2019). "The final multivariate model included covariates of age, sex, length of HIV infection, CD4 nadir, body mass index, and previous cardiovascular disease." (PMID 31622385, 2019). "Resources to prevent cardiovascular disease in sub-Saharan Africa should focus on blood pressure reduction and individuals with a low CD4+ T-cell count during early ART." (PMID 30629187, 2019). "Therapeutic adoptive transfer of natural regulatory T cells (nTreg, CD4+ CD25+ Foxp3+ T cells) or in vivo selective expansion of nTreg cells has been demonstrated to improve the cardiac function in various cardiovascular disease models." (PMID 30770790, 2019). "They showed that age-related comorbidities—particularly cardiovascular diseases and chronic renal disease—were the main prognostic factors for mortality, at the same weight as CD4 cell count." (PMID 30240419, 2018). "An expansion of CD4+CD28null T cells is seen mainly in cytomegalovirus (CMV)-seropositive individuals and has been linked to increased cardiovascular disease risk in other conditions." (PMID 30157919, 2018).
cardiovascular disease (continued). "Since inflammation is known to be a significant contributor to the pathogenesis of cardiovascular disease, we studied the number and function of a novel subset of regulatory T cells, termed CD4+LAP+ Tregs, in patients with ACS." (PMID 24558424, 2014). "Considering the function of CD4 and its lack of association with cardiovascular diseases in our analysis, it is not regarded as a potential drug target." (PMID 40649979, 2025). "The association of HIV-AN with a greater abundance of CD8+ T-cells is particularly relevant given that low CD4/CD8 ratio has been implicated in multiple poor outcomes in people with HIV including neurocognitive disorders, malignancy, and cardiovascular disease." (PMID 39464041, 2025). "In contrast, the risk of recurrence of cardiovascular disease remained low for the patients with low (<1%) CD4+CD28null T-cell levels regardless of statin use, indicating that statins provided limited cardiovascular benefits to these patients." (PMID 38963798, 2024). "It remains unclear, however, whether the risk of cardiovascular disease (CVD) is higher in late HIV presenters (LP; CD4 ≤ 350 cells/μL at HIV diagnosis) compared to PWH diagnosed early." (PMID 37415770, 2023). "To elucidate the impact of cardiovascular disease, DM, and sex on CD4+ T cells in blood, we investigated CD4+ T cells from high-quality frozen peripheral blood mononuclear cells (PBMCs) of 61 men and women with or without DM who underwent cardiac catheterization at the University of Virginia." (PMID 36077273, 2022). "Additionally, the impact of comorbid neurological conditions, other medical conditions, and immunological factors (e.g., cardiovascular disease, hepatitis co-infection, CD4 counts) is difficult to quantify." (PMID 35746623, 2022). "One of our most striking analysis results showed lower CD4 cell counts not to be associated with death due to cardiovascular diseases." (PMID 34886257, 2021). "Along the same line, Terrazini and coworkers showed that most of CMV-specific CD4+ T cells have anti-inflammatory properties and may mediate a beneficial effect in aged individuals regarding cardiovascular disorders." (PMID 33262758, 2020). "Zinc supplementation did not reduce mortality risk, CD4 cell counts, cardiovascular disease risk, and levels of inflammation or microbial translocation in people with heavy alcohol use who are living with HIV/AIDS." (PMID 32383748, 2020). "In patients with no previous history of cardiovascular disease (CVD) a particular insight is provided in the association between impact of CD4/CD8<0.8 and risk prediction of CVD or radiological markers of subclinical CVD." (PMID 25397456, 2014). "Body mass index (BMI) and blood pressure were associated with %CD4, but no traditional cardiovascular disease (CVD) risk factors were associated with %Th1 or %Th2." (PMID 23688675, 2013). "Similar findings were described in a large study which could not find any association between CD4 cell markers and a higher risk of cardiovascular disease death." (PMID 34886257, 2021). "Other covariables included in the multivariate model are sex, age, baseline CD4 T cell count <200 cells/μL or ≥200 cells/μL, 48‐week viral load <50 copies/mL, DM, HBV, cardiovascular disease, and baseline regimen of ANV+3TC+TDF or EFV+3TC+TDF." (PMID 38578026, 2024). "Consistent with this, a link between CMV infection, CD4+CD28− T-cell expansions, and autoimmune and cardiovascular disorders has been previously suggested." (PMID 34576140, 2021). "Comorbidities, especially chronic renal disease and cardiovascular diseases, are becoming increasingly determinant in aging PLHIV, with a prognostic role that is as important as HIV-related prognostic factors such as CD4 cell count." (PMID 29672628, 2018).
cardiovascular disease (continued). "Individuals that maintained CD4+ T-cells within normal ranges and undetectable HIV-1 RNA levels, as a result of HAART, showed a restoration of the immune system function and of PON1 activity, which could lead and conduce to a lower risk for cardiovascular disease." (PMID 24719500, 2014). "We do not find evidence that HIV-positive individuals with a low CD4 count are more likely to die from cardiovascular diseases." (PMID 34886257, 2021). "CD3+CD4+, 0.5649 ± 0.2487 at cardiovascular disease vs 0.7695 ± 0.3274 at no cardiovascular disease, p = 0.001, and CD3+CD4+ αβ T cells, 0.5634 ± 0.2449 vs 0.7802 ± 0.3292, p = 0.001." (PMID 33326443, 2020). "The augment in the frequency of CD4+CD28− T cells, which are highly cytotoxic and producers of pro-inflammatory cytokines such as INF-gamma and TNF-alpha, seems to play a key role in the development of autoimmune and cardiovascular diseases." (PMID 33262758, 2020). "Furthermore, the percentages of peripheral CD4 + CD25 + Foxp3 + Treg and serum IL-10 level were influenced by diabetic complications such as cardiovascular diseases." (PMID 29051757, 2017). "Therefore, routine monitoring of both AIP and hsCRP levels was a good marker of HIV disease progression and cardiovascular disease risk assessment in PLWH, particularly in developing countries where CD4 cell count testing is expensive and not easily available." (PMID 39834358, 2025). "The role of CCR2 in CD4+ T cells in the context of cardiovascular disease has not been elucidated." (PMID 36077273, 2022). "Therefore, CD4+CD28 null cells correlated with CRP and serum albumin levels while important differences in items of CD4+CD28 null and CD8+CD28 null cells were found in patients with cardiovascular disease." (PMID 33816535, 2021). "HIV controllers (HICs) experience relatively low-level viraemia and CD4 preservation without antiretroviral therapy (ART), but also immune activation that may predispose to adverse clinical events such as cardiovascular disease and hospitalization." (PMID 26955965, 2016). "In order to establish potential outcomes of abnormal IA, MT and CD4 cell count observed in the HIV+ women, we sought to determine whether they would correlate with biomarkers of cardiovascular disease (sVCAM-1, sICAM-1) and impaired cognitive function (CXCL10)." (PMID 23724003, 2013). "Diabetic and healthy cells show considerable differences in effector memory CD4+ T cells, with a higher percentage observed in T2DM patients without cardiovascular disease." (PMID 38034011, 2023). "Our study is one of very few reports addressing the issue of CD4+CD25+CD127− T-cells in long-lasting T1D and, notably, in the context of metabolic and early vascular consequences of T1D in young population without clinically apparent cardiovascular disease." (PMID 24348676, 2013).
renal disease (85 papers, 2009 to 2026). "Elevated creatinine levels along with a low CD4+ T cell count were found to be significantly associated with renal disease in HIV-infected individuals in several studies." (PMID 37736888, 2023). "The levels of CD45+ remain comparable in both groups, while the number of CD4+ T cells, associated with inflammation in multiple renal disorders, including salt-sensitive hypertension, was significantly lower in the renal tissue of Li+-treated mice when compared to controls." (PMID 39234304, 2024). "Patients with kidney disease have a compromised immune system with decreased activity of natural killer cells and an imbalanced ratio of CD4+/CD8+ T cells, which may lead to susceptibility to COVID-19 infection." (PMID 39054627, 2024). "Low CD4+ T cell count has been associated with renal disease in HIV-positives patients." (PMID 34556049, 2021). "Similarly, in the murine BXSB-Yaa model of SLE, splenic ICOS+ CD4+ T cell production of IL-21 was linked to renal disease and early mortality." (PMID 27559335, 2016). "In the bivariate logistic regression analysis, factors such as age, smoking, family history of kidney disease, body mass index, and CD4 count demonstrated a p‐value of less than 0.2." (PMID 40950928, 2025). "Patients with HIVAN usually have a CD4 count below 200 cells/mm, while those with HAART-related kidney disease have a CD4 count above 200 cells/mm." (PMID 40097717, 2025). "All the hybrid kidney disease patients, including KTRs, and control individuals established a sustained S-specific CD4+ T-cell response." (PMID 38806532, 2024). "The significance of the CD4+CD28null T cell population in inflammation, vascular, and renal diseases has been appreciated for decades; however, their contribution in the pathogenesis of PCOS and the associated comorbidities is under-explored." (PMID 37109539, 2023). "IL-17RC has also been found to enhance proinflammatory function in kidney disease by regulating CD4+ T cells." (PMID 38045694, 2023). "Despite variability in recipient’s renal disease, our expansion protocol produced Tregs which met all release criteria, expressing >98% CD4+CD25+ with <1% CD8+ and CD19+ contamination." (PMID 29743501, 2018). "Deficiency of CD4+ Tregs is linked to the development of lupus-like disease, while adoptive transfer of CD4+ Tregs slowed the progression of renal disease and reduced mortality in NZB/W F1 mice." (PMID 24864268, 2014). "Urinary CD4+ T-cell counts decreased significantly from 125 (0 to 569 cells/ml) to 0 (0 to 82 cells/ml, P = 0.001) from active renal disease into remission." (PMID 23445537, 2013). "We also observed a significantly lower percentage of CD4+ T cells in patients with active renal disease as compared to patients with inactive disease." (PMID 21708033, 2011). "At day 10 post-cGN induction, mice that received eIF2α-S51D-transduced CD4+ T cells showed a milder renal disease phenotype, as assessed by glomerular crescent scoring and albuminuria measurement, compared to mice that received eIF2α S51A-transduced CD4+ T cells." (PMID 40050432, 2025). "Here we review the literature of CD4+ T cell plasticity focusing on immune-mediated kidney disease." (PMID 33937944, 2021). "The focus of this review has been on the role of CD4+ Foxp3+ Tregs in renal disease." (PMID 29484182, 2018). "A remarkable increase in CD4+ TEM cells in the urinary sediment with a concomitant decrease of circulating CD4+ TEM cells in patients with active renal involvement strongly suggests migration of CD4+ TEM cells during active renal disease into the affected organs." (PMID 25352848, 2014). "In agreement with our data, CD4+ T-cells were increased in active renal disease." (PMID 23445537, 2013). "Overall, we found a negative correlation between CD4 count and renal disease with lower CD4 counts associated with greater risk of renal disease (correlation, r = -0.52)." (PMID 22439731, 2012).
renal disease (continued). "Furthermore, infiltration of CD4+ and CD8+ T-cells seemingly is also important in kidney disease progression, although contradictory results regarding the role of CD4+ T cells exist and the exact role(s) played by inflammatory cells in kidney fibrosis is not delineated." (PMID 27992511, 2016). "In contrast, our data in the model of rUUO in C57Bl/6 suggest that CD4+ T cells or a subpopulation thereof (e.g., Th1 or Treg) may have a protective role in the early stages of kidney disease development; however, any such benefit is overcome in the later stages of disease." (PMID 24489579, 2013). "Surprisingly, controls had relatively low frequencies of S-specific memory CD4+ and CD8+ T-cells pre-vaccination and post-vaccination compared to kidney disease groups, with significantly higher frequencies in patients on dialysis." (PMID 38806532, 2024). "NK cell depletion markedly reduced the number of circulating CD4+ and CD8+ Tregs and exacerbated renal disease in NP-treated mice." (PMID 33391260, 2020). "In order to determine the relations between urinary CD4+ and CD8+ cell counts in different renal diseases, a CD4/CD8 ratio was calculated for urine samples of patients with at least 100 CD3+ cells/dl urine." (PMID 25890061, 2015). "Urine samples from patients with high disease activity (SLEDAI ≥10) and recent biopsy-proven LN (n = 14) or high renal disease activity (SLEDAI ≥10 and renal SLEDAI ≥8, n = 5) had high numbers of both CD4+ (median 1,415 cells/dl urine) and CD8+ T cells (median 1,911 cells/dl urine)." (PMID 25890061, 2015). "Likewise, as we selected HIV “healthy” patients (undetectable viral load and CD4 > 200 cells/3) and without previous renal disease we were anticipating a lower prevalence of CKD." (PMID 22022501, 2011). "Due to the common occurrence of HIV-related kidney diseases in African populations and the current practice of initiating HAART regardless of CD4 cell counts, there has been a noticeable increase in kidney disease prevalence." (PMID 40097717, 2025). "In this study, we investigated the 6-month kinetics of SARS-CoV-2 IgG antibody and specific CD4+ and CD8+ T-lymphocyte levels in patients receiving HD compared with those in individuals without preexisting renal diseases." (PMID 35220855, 2022). "Active SLE patients with renal disorders showed higher OAS2 and OASL expression in PBMCs, OAS3 and OASL expression in CD19+ B cells, and OAS3 expression in CD4+ T cells than patients without the symptoms (P<0.05)." (PMID 32321151, 2020).